LSR (lipolysis stimulated lipoprotein receptor)
Diseases named in the same sentence as LSR in open-access papers (continued):
Sharing a sentence is not in itself a finding about the gene and the disease.
triple-negative breast carcinoma (1 paper, 2025). An invasive breast carcinoma which is negative for expression of estrogen receptor (ER), progesterone receptor (PR), and human epidermal growth factor receptor 2 (HER2). "In this study, we established triple-negative breast cancer cell line models with either LSR overexpression or knockout and investigated the impact of LSR on MDR1 expression and chemoresistance." (PMID 41183038, 2025).
Zinc deficiency (1 paper, 2020). A deficiency of the essential metal Zinc; an essential cofactor for many enzymes. "In this study, zinc deficiency caused by treatment with both TPEN and HMGB1 disrupted the epithelial barrier and induced permeability via downregulation of TJ molecules LSR, TRIC, CLDN-1 and pMAPK in Caco-2 cells in 2.5D cultures." (PMID 33182652, 2020).
cancer (19 papers, 2008 to 2025). A tumor composed of atypical neoplastic, often pleomorphic cells that invade other tissues. "LSR can bind to lipoproteins rich in triglycerides and act as a lipoprotein receptor associated with certain malignant tumors." (PMID 33763152, 2021). "In addition, loss of angulin-1 enhances cancer cell motility and the LSR knockout mice die before embryonic day 15.5 (E15.5), but the cause of death remains unclear." (PMID 34360593, 2021). "Our findings extend previous research on LSR’s function beyond its established role in cell adhesion/junction and lipoprotein endocytosis, underscoring its role in cancer biology and therapeutic responses." (PMID 41183038, 2025). "Recent studies have highlighted LSR’s overexpression in various cancers, including breast, ovarian, and endometrial cancers." (PMID 41183038, 2025). "Our results in this study indicate that LSR overexpression in MDA-MB-231 cells induces cancer cells resistant to doxorubicin and cisplatin." (PMID 41183038, 2025). "While LSR’s role in cancer remains incompletely understood, our anti-LSR mAb offers a valuable tool to investigate its contributions to tumorigenesis, metabolic reprogramming, and immune regulation in future studies." (PMID 41040511, 2025). "Tricellular TJ protein angulin-1/Lipolysis-stimulated lipoprotein receptor (LSR) is an important molecule of tricellular contacts in the epithelial barrier of normal cells and contributes to the malignancy of various cancer cells." (PMID 38338691, 2024). "The function and role of LSR has been studied in various cancers including that of the breast, bladder, and colon." (PMID 35729527, 2022). "This information, in addition to gain and loss of functions experiments, is crucial for deciding if one should activate or inactivate LSR function in cancer patients." (PMID 35586495, 2022). "The lipolysis-stimulated lipoprotein receptor (LSR) displays an important regulatory role in cancer." (PMID 33763152, 2021). "Recently, increasing number of studies have investigated the role of angulin-1/LSR in the development of various cancers." (PMID 34944960, 2021). "It is known that the lipolysis-stimulated lipoprotein receptor (LSR) is overexpressed in cancer cells." (PMID 29865182, 2018). "We previously identified LSR as a novel therapeutic target by analyzing cell surface membrane proteins of normal cell and cancer cell lines using iTRAQ-based quantitative proteomics." (PMID 30250639, 2018). "Here, we aimed to study in a mouse xenograft model the consequences of LSR knockout on tumor growth of two colon-derived cancer cell lines (CaCo-2 and HCT116)." (PMID 27391068, 2017). "Lipolysis-stimulated lipoprotein receptor (LSR) is a unique molecule of tricellular contacts of normal and cancer cells." (PMID 28071680, 2017). "Identification of potential LSR-dependent signaling pathways or interaction partners will be crucial for placing the (patho)physiological roles of LSR in cancer into a coherent picture." (PMID 27391068, 2017). "The downregulation of LSR markedly promoted cancer cell migration, invasion and proliferation compared to control cells." (PMID 27036040, 2016). "Previous studies have determined that LSR and CD44 have multiple variants/isoforms that occur in cancer." (PMID 24990559, 2014). "In conclusion, our in vitro experiment indicated that knock down of LSR affected genes known to be involved in cancer and especially cellular movements like invasion, migration and motility." (PMID 18647386, 2008). "Our anti-LSR mAb selectively acts on cancer cells expressing LSR and has little toxicity to normal tissues, indicating that it might be a more effective and safer agent than these kinase inhibitors." (PMID 35729527, 2022). "Hence, more detailed investigations of LSR-mediated lipid metabolism as related to cancer cell proliferation is required in order to develop new therapeutic agent targeting LSR." (PMID 30250639, 2018).
cancer (continued). "Knockdown of LSR increases cell motility and invasion of certain cancer cells." (PMID 27036040, 2016). "However, little is known about the regulation of LSR expression in cancer cells." (PMID 27036040, 2016). "Angulin-1/LSR and AREG are highly expressed in some cancer cells indicated gland-like structures in EEC tissues." (PMID 34944960, 2021). "Expression of LSR (A), S100A14 (B) and DPYSL3 (C) in breast, prostate and others (retinal pigment, liver, colon and esophageal) cancer cell lines from QN + SVA normalized integrated data." (PMID 28651527, 2017). "The localization of LSR expression was predominatly on the cell membrane, however, similar to the pattern in the MCF7 cancer cell line LSR was also prominent in the cytoplasm." (PMID 24637461, 2014). "Furthermore, we showed that LSR and subsequent MAPK regulated the expression of MMPs, which are endopeptidases involved in cell invasion and migration of various cancers by degrading the basement membrane and extracellular matrix." (PMID 35729527, 2022).
tumor (14 papers, 2008 to 2025). "One study using TNBC xenografted mouse models revealed that LSR overexpression has been linked to tumor development." (PMID 41040511, 2025). "In this study, we analysed the association between LSR expression and prognosis in patients with GC, and evaluated the anti-tumor effects of anti-hLSR mAb (#1–25) in vitro and in vivo." (PMID 30250639, 2018). "At first, we studied the tumor-promoting role of LSR in a mouse xenograft model with wild-type and LSR-deficient HCT116 and CaCo-2 cells." (PMID 27391068, 2017). "Furthermore, LSR is implicated in tumor growth and metastasis." (PMID 41465326, 2025). "Thus, LSR deficiency might hamper tumor xenograft growth of CaCo-2 cells by leading to decreased angiogenesis and, consequently, to cell death induced by (oxygen) undersupply." (PMID 27391068, 2017). "In this study, we established isogenic TNBC cell lines with LSR overexpression and characterized the effect of LSR dysregulation on tumor cell aggressiveness and therapeutic responsiveness." (PMID 41183038, 2025). "Amongst the differentially expressed EMT genes from that study, we find overlap with PTPRK-regulated genes including TGFB1, COL6A1, GPX3 and KLK10, as well as genes encoding LSR and PKP2, both of which are hyperphosphorylated in PTPRK KO tumours." (PMID 38904097, 2024). "Anti-LSR mAb significantly inhibited the tumor growth in EC cell xenograft mouse model (tumor volume, 407.1 mm3versus 726.3 mm3, p = 0.019)." (PMID 35729527, 2022). "Anti-LSR mAb significantly inhibited tumor growth compared with control Ab (mean tumor volume, 407.1 mm3versus 726.3 mm3, p = 0.019)." (PMID 35729527, 2022). "To investigate if and how LSR regulates tumor growth, we knocked down and overexpressed LSR in human HCC cell lines." (PMID 35586495, 2022). "Key findings of our study were that LSR was associated with tumor growth, invasion, metastasis, and poor prognosis through MAPK signaling in EC, and that our anti-LSR mAb had a potential to be a novel therapeutic agent for EC." (PMID 35729527, 2022). "Our results suggest that LSR contributes to tumor growth, invasion, metastasis, and poor prognosis of EC through MAPK signaling." (PMID 35729527, 2022). "The authors provided further evidence of LSR-mediated VLDL uptake; LSR-dependent cell proliferation in response to VLDL; anti-tumor activity from LSR blockade; and an association between high LSR and poor prognosis in OC patients." (PMID 34518593, 2021). "Due to the observed differences in tumor growth and cell proliferation, we focused our attention on CaCo-2 wild-type and LSR knockout cells." (PMID 27391068, 2017). "We show that LSR was expressed in epithelium, endothelium, and stromal cells within the healthy breast tissue, as well as in tumor epithelium." (PMID 24637461, 2014). "Moreover, the anti-LSR mAb demonstrated modest therapeutic potential as a standalone agent, slightly reducing tumor growth and inhibiting lipid uptake and synthesis." (PMID 41040511, 2025). "Interestingly, some studies recently suggested that LSR is involved in tumor initiation and progression." (PMID 35586495, 2022). "First, to the best of our knowledge, this study is the first to demonstrate that LSR contributes to tumor growth, invasion, metastasis, and poor prognosis through MAPK signaling in EC; this finding was obtained using a large number of clinical samples, multiple cell lines, and proteomic data." (PMID 35729527, 2022). "Integrating results across our tumor gene expression analysis and plasma/ascites lipidomics profiling studies provides support for a model of altered lipoprotein uptake in OC relative to benign tumors, mediated in part through the membrane receptor LSR." (PMID 34518593, 2021). "Our previous results showed the treatment with anti-human LSR (hLSR) monoclonal antibody (mAb), which we previously generated a chicken–mouse chimeric mAb (#1–25, Fc type is mouse IgG2a), has a potential to inhibit tumor growth in ovarian cancer." (PMID 30250639, 2018).
tumor (continued). "Recently, the lipolysis stimulated lipoprotein receptor (LSR) was reported to be highly expressed in cells resistant to chemotherapy in vitro and correlated with tumor-initiating capacity in vivo using CD44hi/24lo epithelioid basal A cells derived from a triple negative cell line." (PMID 24637461, 2014). "In addition, this study demonstrated that knockdown of LSR could increase the expression of pro-oncogenic genes, such as interleukin 1 alpha and endothelin 1, which could contribute to tumor initiation and progression." (PMID 35586495, 2022). "Furthermore, we demonstrated that an anti-LSR mAb which we developed inhibited tumor growth involved in lipid uptake, and that its antitumor effect was a direct manner, independent of antibody-dependent cellular cytotoxicity and complement-dependent cytotoxicity." (PMID 35729527, 2022). "In summary, the present study elucidates the multifaceted role of LSR in TNBC, particularly highlighting its contributions to tumor aggressiveness and chemoresistance." (PMID 41183038, 2025). "Knockdown of LSR significantly increased the expansion of HCC cells and significantly promoted tumor growth." (PMID 35586495, 2022). "We believe that LSR upregulates MAPK signaling and promotes cell invasion and migration via MT1-MMP and MMP2 in EC cells in this tumor microenvironment." (PMID 35729527, 2022). "In vitro and in vivo experiments also demonstrate that LSR inhibits HCC cell expansion and reduced tumor growth." (PMID 35586495, 2022). "Moreover, overexpression of LSR altered gene expression of pathways involved in transformation and tumorigenesis as well as enhanced proliferation and survival in anchorage independent conditions, highlighting that reestablishment of LSR signaling promotes aggressive/tumor initiating cell behaviors." (PMID 24637461, 2014). "EGR1 was upregulated upon knockdown of LSR in vitro and upregulated when comparing tumor samples with normal urothelium samples, though not significantly." (PMID 18647386, 2008). "However, regulatory functions may also be possible as it was shown that LSR expressed on tumor cells had a negative effect on CD8+ T cell function and activation, which could only be rescued by blocking LSR with antibodies." (PMID 38732086, 2024).
infection (2 papers, 2024). The state of being infected such as from the introduction of a foreign agent such as serum, vaccine, antigenic substance or organism. "We next analyzed whether LSR downregulation in infected cells was also a consequence of translational shutoff triggered by infection." (PMID 39443717, 2024). "LSR downregulation in infected cells is not only a specific effect induced by the Spike protein, but also a consequence of the translational shutoff triggered by the infection." (PMID 39443717, 2024). "When Caco-2 cells and hACE2-HIEC-6 were exposed to 1 multiplicity of infection (MOI) of VSV-SARS-CoV-2, LSR downregulation was observed (C and EV1B)." (PMID 39443717, 2024). "The results showed that LSR levels were significantly decreased in Caco-2 cells overexpressing M protein, NSP1, or NSP14, indicating that translational shutoff triggered by infection also contribute to the LSR downregulation in infected cells." (PMID 39443717, 2024). "The data presented in this work identify LSR as a therapeutic target in the management of COVID-19 and open up new avenues for blocking the binding of Spike to ACE2 through LSR for the prevention of infection with SARS-CoV-2 as well as other viruses that use ACE2 for cell entry." (PMID 39443717, 2024).
LSR also shares sentences with these, for which no sentence is quoted: adenocarcinoma (2 papers); Crohn disease (2); head and neck cancer (2); atherosclerosis (1); benign tumors (1); colorectal adenoma (1); colorectal cancer (1); inflammatory bowel disease (1); lymph node metastasis (1); progressive familial intrahepatic cholestasis (1); type 2 diabetes (1); ulcerative colitis (1).